CNTNAP3C (contactin associated protein family member 3C)
Gene: Protein-coding gene on chromosome 9 (61,330,717 to 61,453,030, forward strand). Ensembl gene ENSG00000283378.
Homologues: Orthologues: chimpanzee CNTNAP3 (94% identical), rat Cntnap3 (71% identical), mouse Cntnap3 (70% identical), tropical clawed frog cntnap4 (57% identical), zebrafish cntnap3 (48% identical). Paralogues in human: CNTNAP3 (100% identical), CNTNAP3B (98% identical), CNTNAP4 (72% identical), CNTNAP5 (56% identical), CNTNAP2 (46% identical), CNTNAP1 (35% identical), NRXN2 (26% identical), NRXN1 (23% identical), NRXN3 (23% identical), CUBN (15% identical), HEPHL1 (14% identical), CP (14% identical), and 23 more.